OR7E47P (olfactory receptor family 7 subfamily E member 47 pseudogene)
Synonyms: OR7E141
Gene: Transcribed unprocessed pseudogene on chromosome 12 (52,107,278 to 52,108,261, forward strand). Ensembl gene ENSG00000257542.
Diseases named in the same sentence as OR7E47P in open-access papers:
OR7E47P is named in the same sentence as 1 disease in open-access papers, as found by Europe PMC text mining. Sharing a sentence is not in itself a finding about the gene and the disease.
OR7E47P shares sentences with these, for which no sentence is quoted: tumor (1 paper).